VEGFA (vascular endothelial growth factor A)
Diseases named in the same sentence as VEGFA in open-access papers (continued):
Sharing a sentence is not in itself a finding about the gene and the disease.
medulloblastoma (20 papers, 2010 to 2025). A malignant, invasive embryonal neoplasm arising from the cerebellum. "In the literature, SPARC overexpression has been correlated with six miRNAs involved in medulloblastoma progression, whereas the reciprocal modulation between VEGFA and SPARC proteins has been related to tumor growth." (PMID 39000404, 2024). "Among the genes displaying a higher spatial variance in LFS as compared to sporadic medulloblastomas, angiogenesis factor VEGFA was prominent." (PMID 39609432, 2024). "Expression of VEGFA in xenografted medulloblastoma cells was further confirmed with in situ hybridization." (PMID 28417956, 2017). "Several studies showed that the ISR stimulates angiogenesis in tumors, including medulloblastoma, by enhancing the expression of vascular endothelial growth factor A (VEGF-A)." (PMID 27802424, 2016). "To investigate if the VEGFA observation has clinical relevance, we screened a dataset of 423 medulloblastomas for expression of VEGFA, and similarly found that VEGFA was preferentially expressed in Group 3 medulloblastomas compared to other subgroups (Anova p = 1.7e-17)." (PMID 28417956, 2017). "Interestingly, we found that the tissue level of VEGFA in MB-LU-181 (depicted as Group 3 in graph) greatly exceeded VEGFA levels in 4 primary medulloblastomas of other molecular subgroups that were analysed in parallel." (PMID 28417956, 2017). "In cultured medulloblastoma spheres, only IL-8, IL-16 and VEGFA were detected." (PMID 28417956, 2017). "Our previous study showed that the UPR is activated in tumor cells in a mouse model of medulloblastoma and that GADD34 inactivation enhances PERK signaling and facilitates the medulloblastoma formation by promoting angiogenesis through induction of vascular endothelial growth factor A (VEGF-A)." (PMID 25794107, 2015). "VEGFA, COX-2 and c-Myc are highly expressed in Group 3 compared to other medulloblastoma subgroups, suggesting that these molecules are relevant therapeutic targets in Group 3 medulloblastoma." (PMID 28417956, 2017). "Combination of VEGFA and HIF-1α inhibitors could provide a synergistic combination therapy against medulloblastoma." (PMID 37568705, 2023). "In addition, we demonstrate increased expression of the relevant therapeutic targets vascular endothelial growth factor A (VEGFA) and cyclooxygenase-2 (COX-2) in Group 3 medulloblastoma patients." (PMID 28417956, 2017). "Also, high levels of VEGFA were detected in both cells and supernatants from MB-LU-181 neurospheres compared to human dermal fibroblast (HDF) cells and cell lines from other medulloblastoma subgroups (Anova, p < 0.0001 for both cells and supernatants)." (PMID 28417956, 2017). "In addition to VEGFA, emerging evidence suggests that hypoxia-inducible factor 1 alpha (HIF-1α) may also play a critical role in medulloblastoma pathogenesis." (PMID 37568705, 2023). "In SHH medulloblastoma, the downregulation of miR-466f-3p, together with the concordant upregulation of VEGFa and Neuropilin 2, encouraged cell proliferation and the self-renewal ability of CSCs through the EMT process, which sustained the mesenchymal phenotype of SHH medulloblastoma CSCs." (PMID 37370764, 2023). "Our results from a gene expression analysis of 423 medulloblastomas further demonstrates enhanced expression of VEGFA in Group 3 compared to other medulloblastoma subgroups, indicating that this patient group in particular may benefit from VEGF-targeted therapies." (PMID 28417956, 2017).
periodontal disease (20 papers, 2012 to 2025). "In the case of periodontal diseases, miR-203 plays a crucial role in this change by targeting vascular endothelial growth factor A (VEGFA), thereby inhibiting angiogenesis." (PMID 39125843, 2024).
polycystic ovary syndrome (20 papers, 2005 to 2025). A disorder that manifests as multiple cysts on the ovaries. "Its inhibition of angiogenesis has also been described in benign diseases such as polycystic ovarian syndrome through targeting of VEGFA." (PMID 34205829, 2021).
polyp (20 papers, 2006 to 2025). A usually exophytic mass attached to the underlying tissue by a broad base or a thin stalk. "Specifically, compared with normal tissues, monocytes, pDCs and epithelial subsets had increased expression levels of VEGFA and/or VEGFB, while endothelial cells had increased expression levels of VEGF receptors FLT1 and KDR in three polyp subtypes." (PMID 38264936, 2024).
vascular dementia (20 papers, 2014 to 2025). A degenerative vascular disorder affecting the brain. "In the Esther study, VEGFA was associated with vascular dementia with associations stronger in ε4 negative participants." (PMID 37584418, 2023).
acute lymphoblastic leukemia (19 papers, 2006 to 2025). Leukemia with an acute onset, characterized by the presence of lymphoblasts in the bone marrow and the peripheral blood. "Vascular endothelial growth factor‐A (VEGF‐A), In combination with other pro‐angiogenic factors, plays a pivotal role in angiogenesis and the pathogenesis of acute lymphoblastic leukemia (ALL)." (PMID 40944395, 2025).
Hypercholesterolemia (19 papers, 2011 to 2024). An increased concentration of cholesterol in the blood. "In patients, hypercholesterolemia was associated with decreased vascular endothelial growth factor-A plasma levels during early follow up after renal transplantation and increased chronic graft dysfunction." (PMID 30642356, 2019). "We hypothesized that hypercholesterolemia could affect vascular repair processes and promote post-transplant renal vascular remodeling through the over-expression of the anti-angiogenic thrombospondin-1 interacting with vascular endothelial growth factor-A levels." (PMID 30642356, 2019).
laryngeal carcinoma (19 papers, 2009 to 2026). Carcinoma that arises from the laryngeal epithelium. "Interestingly, the decrease in VEGFA expression after miR-17-5p transfection correlates with a previous study on laryngeal cancer, in which miR-17-5p is shown to reduce PI3KR1 expression." (PMID 35806488, 2022). "Two of them (VEGFA rs13207351 and FAS rs2234768) were associated with overall survival for patients with laryngeal cancer and NPC, respectively, with VEGFA rs13207351 showing the most promise for its prognostic value in the subgroup of laryngeal cancer patients." (PMID 33800431, 2021). "High VEGFA expression, especially in combination with high EGFR expression has earlier been linked to local recurrence in TSCC in one study, and likewise in oral and laryngeal cancer, but not in a third study, including HPV-positive and HPV-negative OPSCC." (PMID 29587383, 2018).
papillary thyroid cancer (19 papers, 2010 to 2024). "The aim of the present study was to investigate whether genetic variants in the vascular endothelial growth factor A gene (VEGFA) were risk factors for papillary thyroid carcinoma (PTC) or nodular goiter (NG) in Han Chinese." (PMID 28178662, 2017). "The present study shows that tissues affected by papillary thyroid cancer or colloid goiter, and their respective adjacent tissues present increased expression of VEGFA and NFE2L2, thereby providing evidence that vascularization and oxidative stress are imbalanced in these tissues." (PMID 32824922, 2020). "In order to evaluate the involvement of VEGFA, NFE2L2, hsa-miR-17-5p, and hsa-miR-612 in thyroid pathology, we examined tissue samples from colloid goiter, papillary thyroid cancer (PTC), and a normal thyroid." (PMID 32824922, 2020). "Of note, among the downregulated genes MMP2, VEGFA, CCND1, and TWIST1 were downregulated only in papillary carcinoma but were either unchanged or upregulated in other two subtypes." (PMID 30863721, 2019).
chronic lymphocytic leukemia (18 papers, 2004 to 2024). "Angiogenesis process contributes to the pathogenesis of B-cell chronic lymphocytic leukemia (B-CLL) being the levels of VEGFA and bFGF higher in patients than in healthy controls." (PMID 32585853, 2020). "The angiogenesis process makes a significant contribution to the pathogenesis of B-cell chronic lymphocytic leukemia (B-CLL), the levels of VEGFA and bFGF being higher in patients than in healthy people." (PMID 36186463, 2022). "Deregulation of miR-30d was observed in chronic lymphocytic leukemia, where it exerts its pro-angiogenic function, at least in part, by inhibiting MYPT1, which in turn, increased phosphorylation levels of c-JUN and activates the VEGFA-induced signaling cascade." (PMID 32937758, 2020).
Hepatic steatosis (18 papers, 2016 to 2025). Steatosis is a term used to denote lipid accumulation within hepatocytes. "It is reported that hypoxia in hepatocytes led to an increased expression of HIF-1α and VEGFA, which further aggravated liver injury as was confirmed in studies of alcoholic fatty liver although minimal research was done in terms of NAFLD." (PMID 36506575, 2022). "While silencing of FABP1 directly ameliorates hepatic steatosis, its effect on HCC development seems to depend more on increased secretion of vascular endothelial growth factor-A (VEGF-A), therefore promoting angiogenesis." (PMID 37063269, 2023). "In addition, BAT-specific VEGFA transgenic mice display improved glucose and lipid metabolism as well as a decrease in HFD-induced hepatic steatosis." (PMID 37894852, 2023).
kidney (18 papers, 2011 to 2025). "Interestingly, miR‐195‐5p alleviates acute kidney injury through repression of inflammation and oxidative stress by targeting VEGFA." (PMID 34592792, 2021). "A bioinformatics analysis reveals that vascular endothelial growth factor A (VEGFA) and its regulatory TF SP2 exert important effects on the development of clear cell sarcoma of the kidney." (PMID 39850832, 2025).
lung squamous cell carcinoma (18 papers, 2007 to 2025). "LINC00173.v1 aggravated angiogenesis and progression of lung squamous cell carcinoma by inhibiting miR-511-5p induced VEGFA degradation." (PMID 35740511, 2022). "Overexpressed LINC00173.v1 in lung squamous cell carcinoma upregulated VEGFA, promoting angiogenesis and tumor progression." (PMID 35740511, 2022). "Previous study had found that LINC00173 promotes the proliferation and migration of vascular endothelial cells in lung squamous cell carcinoma by acting as ceRNA to bind with miR-511-5p and regulate VEGFA expression." (PMID 34603387, 2021). "Reduced miR-511-5p has also been found in lung squamous cell carcinoma, and miR-511-5p overexpression could effectively block the angiogenesis of the tumor via impeding the expression of VEGFA." (PMID 35186236, 2022).
Myocardial fibrosis (18 papers, 2012 to 2025). "In contrast, VAL had less evident effects than SAC/VAL on angiogenic tracer uptake, prevention of myocardial fibrosis, attenuation of cardiomyocyte growth and VEGFA expression." (PMID 30962467, 2019). "The cardiac expression of VEGFA was found to significantly positively correlate with that of LOXL2 in the present study, which may be associated with the stimulation of microangiogenesis in response to LOXL2-induced myocardial fibrosis." (PMID 38883603, 2024). "Furthermore, at the cellular level, SAC/VAL attenuated cardiomyocyte growth and increased capillary/cardiomyocyte ratio in the border zone and prevented myocardial fibrosis in the remote zone, while at the molecular level induced VEGFA expression in the border zone." (PMID 30962467, 2019). "S. miltiorrhiza Bunge alleviated the damage to cardiac function, attenuated myocardial fibrosis and protected endothelial cell function by increasing the expression of TGF‐β and VEGFA." (PMID 37643320, 2023).
renal dysfunction (18 papers, 2012 to 2025). "Polymorphisms in the vascular endothelial growth factor A (VEGFA) gene exacerbate the risk of renal dysfunction under co-exposure to lead and cadmium." (PMID 41394865, 2025).
synovitis (18 papers, 2008 to 2025). Inflammation of a synovial membrane. "The key finding of this study was that lower levels of pre-operative synovitis and higher levels of IL-6 and VEGFA were associated with better post-operative outcomes in UKA patients." (PMID 37449990, 2023). "Lower levels of synovitis and higher levels of IL-6 and VEGFA were associated with better post-operative outcomes after UKA, which could be helpful for identifying UKA patients in clinical practice." (PMID 37449990, 2023). "However, overexpression of VEGFA will lead to the abnormal proliferation of synovium and the aggravation of synovitis." (PMID 31988808, 2020).
Thromboembolism (18 papers, 2008 to 2025). The formation of a blood clot inside a blood vessel that subsequently travels through the blood stream from the site where it formed to another location in the body, generally leading to vascular occlusion at the distant site. "When investigating the association between thromboembolism/recurrent spontaneous abortions and SNP, the p value for VEGFA rs2010963 polymorphism was 0.7486, and Pearson’s Chi-squared test (X-squared) was 0.57917." (PMID 36362759, 2022).
ulcerative colitis (18 papers, 2007 to 2025). An inflammatory bowel disease involving the mucosal surface of the large intestine and rectum. "The bacteriostatic effects induced on Gram+ and Gram- strains, together with the inhibition of COX-2, TNFα, HIF1α, and VEGFA in the colon, suggest the potential of P. mahaleb water extract in contrasting the clinical symptoms related to ulcerative colitis." (PMID 34361576, 2021). "In this regard, the bacteriostatic effects induced on Gram+ and Gram- strains, together with the inhibition of COX-2, TNFα, HIF1α, and VEGFA suggest the potential of P. mahaleb water extract in contrasting the clinical symptoms related to ulcerative colitis." (PMID 34361576, 2021). "For example, VEGFA overexpression was related with ulcerative colitis and various signaling pathways according to KEGG enrichment results." (PMID 31383782, 2019). "A prior study has revealed that overexpressed VEGFA in ulcerative colitis accelerates inflammatory angiogenesis of the colon, thus promoting the progression of ulcerative colitis." (PMID 31383782, 2019).
lupus nephritis (17 papers, 2014 to 2025). Glomerulonephritis in the context of systemic lupus erythematosus. "For instance, in patients with lupus nephritis, VEGF expression in the kidneys is considered a marker of renal injury and can predict the risk of short-term renal function loss, further supporting VEGFA’s potential as a biomarker." (PMID 41476974, 2025).
steatosis (17 papers, 2016 to 2025). Increased lipid within the cytoplasm of cells. "The current study highlights the different effects and signaling pathways of VEGFA in liver surgery requiring PH and I/R based in the presence of steatosis." (PMID 31254006, 2019). "Next, we evaluated whether, in addition to the benefits in terms of APT, glycogen and phospholipids induced by the lipid treatment in steatotic livers, changes in growth factors (HGF, IGF1 and VEGFA) could explain the enhanced benefits conferred by the lipid treatment in the presence of steatosis." (PMID 34444713, 2021). "The inhibition of either NRG1 or PAK1 (BD+anti-NRG1+LT and BD+anti-PAK1+LT groups) decreased VEGFA in non-steatotic livers, while no changes were observed in the presence of steatosis when compared with the results obtained in the BD+LT group." (PMID 35625715, 2022). "We postulated that the expression and role of VEGFA as well as the mechanisms by which VEGFA might affect damage or regeneration might differ depending on the hepatic surgical conditions as well as the presence or absence of steatosis in the liver submitted to surgery." (PMID 31254006, 2019).
Allergy (15 papers, 2012 to 2025). An allergy is an immune response or reaction to substances that are usually not harmful. "It is found that there are 50 potential targets of PLP in allergy, which were imported into the String database to establish PPI, among which the top 5 interaction relationships according to the number are: INS, TNF, CAT, MAPK1 and VEGFA." (PMID 35879791, 2022).
gastrointestinal stromal tumor (15 papers, 2010 to 2026). "Overexpressed KDM4D in gastrointestinal stromal tumor depended on HIF1β to promote VEGFA signaling pathway." (PMID 34820329, 2021).
intracerebral hemorrhage (15 papers, 2007 to 2024). A cerebrovascular disorder characterized by bleeding into one or both cerebral hemispheres including the basal ganglia and the cerebral cortex. "VEGFA has been shown to be one of the upregulated angiogenic factors in ruptured IA and can accelerate injury by intracerebral hemorrhage injury." (PMID 37573538, 2024).
leiomyoma (15 papers, 2007 to 2026). A well-circumscribed benign smooth muscle neoplasm characterized by the presence of spindle cells with cigar-shaped nuclei, interlacing fascicles, and a whorled pattern. "In leiomyomatous cell lines, miR-200c interaction with VEGFA has been shown and accordingly, in leiomyomas as well as in PTSMT, very low levels of miR-200c correlate with increased levels of VEGFA." (PMID 23830214, 2013).
nasal polyp (15 papers, 2014 to 2024). "This is consistent with several reports identifying increased VEGF in nasal polyp tissue, and in the lower airway VEGFA from EpCs has been implicated in signaling to endothelial cells to promote angiogenesis in obstructive lung disease." (PMID 38444858, 2024).
non-Hodgkin lymphoma (15 papers, 2010 to 2025). Distinct from Hodgkin lymphoma both morphologically and biologically, non-Hodgkin lymphoma (NHL) is characterized by the absence of Reed-Sternberg cells, can occur at any age, and usually presents as a localized or generalized lymphadenopathy associated with fever and weight loss. "Since rituximab targeting CD20 was first approved for Non-Hodgkin’s lymphoma (NHL) in 1997, the US Food and Drug Administration (FDA) has approved a variety of therapeutic monoclonal antibodies, which can target CD19, HER-2, VEGFA, EGFR, and CD52, etc.." (PMID 36304470, 2022).
pituitary cancer (15 papers, 2014 to 2025). A primary or metastatic malignant neoplasm affecting the pituitary gland. "Bevacizumab-800CW targets vascular endothelial growth factor A (VEGF-A) and is a promising tracer, since it is overexpressed in PitNETs with CS invasion, lactotroph PitNETs, and pituitary carcinomas." (PMID 39390132, 2025).
rhabdomyosarcoma (15 papers, 2003 to 2024). A rare aggressive malignant mesenchymal neoplasm arising from skeletal muscle. "This included a solid pseudopapillary neoplasm of pancreas (everolimus for high Ras homolog enriched in brain (RHEB)), EPN (bevacizumab for high VEGFA) and rhabdomyosarcoma (temsirolimus/vinorelbine/cyclophosphamide for high AKT2)." (PMID 38844796, 2024). "CCND2, HOXC6, PLXNA1, and Vascular Endothelial Growth Factor A (VEGFA) were also highly expressed in a large fraction of human primary RMS, supporting prominent roles for these genes in rhabdomyosarcoma." (PMID 24009521, 2013).
acute coronary syndrome (14 papers, 2011 to 2025). Signs and symptoms related to acute ischemia of the myocardium secondary to coronary artery disease. "It was reported that inflammation and neovascularization in atheromatous plaques might be mediated by VEGFA, and the antihuman IL-6 receptor monoclonal antibody was shown to improve endothelial function in patients with acute coronary syndromes." (PMID 31619994, 2019).
AIDS (14 papers, 2011 to 2024). A syndrome resulting from the acquired deficiency of cellular immunity caused by the human immunodeficiency virus (HIV). "Collectively, these findings support previous reports that increased inflammation may follow or induce non-AIDS comorbidities, and further pinpoint PD-L1, VEGFA, LAP TGFβ-1, and TNFRSF9 as possible targets to decrease the risk for malignancies in well-treated PLHIV." (PMID 36157576, 2022).